HIPK2 (homeodomain interacting protein kinase 2)
Diseases named in the same sentence as HIPK2 in open-access papers (continued):
Sharing a sentence is not in itself a finding about the gene and the disease.
cancer (continued). "A better understanding of the mechanisms of GEM indicate that it activates HIPK2, p38 MAPK, DYRK2 and PKC kinases, which are involved in p53Ser46 phosphorylation, executing cell apoptosis in response to DNA damage in various cancers." (PMID 33531986, 2021). "The coactivator function of HIPK2 for estrogen receptor-mediated gene expression discovered here might also be of pathophysiological relevance, as revealed by the analysis of gene dependency screens for 712 cancer cell lines spanning 3 large-scale RNAi datasets." (PMID 32984337, 2020). "HIPK2 knockdown also leads to HIF-1-mediated cyclooxygenase-2 (COX-2) up-regulation, which has been found to promote invasion in many types of cancer." (PMID 28107201, 2017). "Homeodomain-interacting protein kinase-2 (HIPK2) was reported to inhibit HIF-1α, thereby suppressing MDR1 gene transcription and sensitize cancer cells to doxorubicin-induced apoptosis." (PMID 24358977, 2013). "This modification enhances HIPK2’s ability to phosphorylate HP1γ, promoting DNA repair, and inhibits INF2-mediated mitochondrial fission, thereby reducing the proliferation and invasion of cancer cells." (PMID 40391156, 2025). "Intriguingly, the lack of HIPK2 activity induces a pseudo-hypoxic phenotype in cancer cells that contributes to cancer cell invasion." (PMID 37892171, 2023). "Based on the Cancer Genome Atlas (TCGA) cancer database, we used LASSO regression analysis to identify the six prognostic-related genes with both DDR and EMT functions, including TP63, YWHAZ, BRCA1, CCND2, YWHAG, and HIPK2." (PMID 36673982, 2023). "Homeodomain-interacting protein kinase 2 (HIPK2) is a protein kinase that controls several molecular pathways involved in cell death and development and it has been extensively studied, mainly in the cancer biology field." (PMID 36831402, 2023). "It has been shown that HIPK2 can suppress HIF1α/VEGF signaling to decrease angiogenesis and the degradation of HIPK2 leads to enhanced HIF1α/VEGF signaling and angiogenesis is a key mechanism of cancer progression." (PMID 34963484, 2021). "Zinc up-regulated HIPK2 to inhibit COX-2 level, leading to reduced cancer growth." (PMID 28107201, 2017). "Although this association needs to be further investigated, it opens up to the possibility that HIPK2 reduction/inactivation might contribute to tetraploidization and CIN in this type of cancer." (PMID 25868975, 2015). "In conclusion, our data support a model in which, at the end of cell division, HIPK2 controls abscission acting on midbody regulation and MBR removal, this latter at least through autophagy-mediated degradation with clinical implication in cancer and in neurodegenerative diseases." (PMID 33043004, 2020). "However, the molecular mechanism of HIPK2 in regulating chemoresistance of cancer cell is not fully understood." (PMID 24846322, 2014). "However, the exact role of HIPK2 in the development and progression of human cancer is not clear yet." (PMID 21698151, 2011).
cancer (continued). "However, the role of HIPK2 in regulating chemoresistance of cancer cell is not fully understood." (PMID 24846322, 2014).
kidney disease (11 papers, 2015 to 2024). "Using the unbiased systems biology approach, we previously identified HIPK2 as a pivotal signaling modulator of kidney disease and fibrosis progression." (PMID 38512421, 2024). "The HIPK2 protein level increased in the kidneys of HIV transgenic mice (Tg26 mice) as well as in those of patients with various kidney diseases." (PMID 36831402, 2023). "Global KO of HIPK2 attenuates kidney injury and fibrosis in several animal models of kidney disease." (PMID 32701510, 2020). "Although these data strongly support the role of HIPK2 as a key driver of fibrosis in kidney disease, the effect of HIPK2 function in renal tubular epithelial cells (RTECs) or other cell types in this process was unclear." (PMID 32701510, 2020). "HIPK2 is upregulated in fibrosis in murine kidney disease and in human HIVAN, focal segmental glomerulosclerosis, diabetic nephropathy and IgA nephropathy." (PMID 25972814, 2015). "Collectively, our findings indicate that the HIPK2-CT is involved in the regulation of nuclear NF-κB transcriptional activity and that HIPK2-CT or its analogs could be further exploited as potential antiinflammatory agents to treat kidney disease." (PMID 38512421, 2024).
neurological diseases (6 papers, 2023 to 2024). "Here, we review the data about the role of HIPK2 in neuronal development, survival, and homeostasis, highlighting the implications in the pathogenesis of neurological disorders, and pointing out HIPK2 potentiality as therapeutic target and diagnostic or prognostic marker." (PMID 36935052, 2023). "At the same time, a systematic analysis of large cohorts of patients will be fundamental to evaluate how frequently HIPK2 is deregulated and/or mutated in neurological diseases, and subsequently propose it as a diagnostic or prognostic marker in clinical practice." (PMID 36935052, 2023). "At the same time, HIPK2 is involved in several neurological disorders, by impacting crucial cellular processes, such as the regulation of neuronal cell death and protein turnover." (PMID 36935052, 2023). "Acting through similar context- and stage- dependent molecular mechanisms in both oncological and neurological diseases, HIPK2 is one of these factors." (PMID 36935052, 2023). "•Altered HIPK2 functions are found in different neurological disorders." (PMID 36935052, 2023). "HIPK2 has also been involved in regulating fibrosis, angiogenesis, and neurological diseases." (PMID 37345014, 2023). "However, further investigations that could fully elucidate the different mechanisms through which HIPK2 is involved in the pathogenesis of neurological disorders, would be needed to concretely estimate the real translational potential of this factor." (PMID 36935052, 2023). "Moreover, HIPK2 is involved in processes, such as endoplasmic reticulum stress response and protein aggregate accumulation, and pathways, including TGF-β and BMP signaling, that are crucial in the pathogenesis of neurological disorders." (PMID 36935052, 2023).
neurodegenerative disease (5 papers, 2015 to 2023). A disorder of the central nervous system characterized by gradual and progressive loss of neural tissue and neurologic function. "However, it is important to note that HIPK2 also has some onco-suppressor functions and that loss of HIPK2 may also lead to neurodegenerative disease." (PMID 25972814, 2015). "Whereas, the HIPK2 has also been reported in neurodegenerative diseases via endoplasmic reticulum (ER) stress." (PMID 36590916, 2022).
cardiac disease (2 papers, 2021 to 2023). "Moreover, our data suggest the possible involvement of HIPK2 in the pathogenesis of multiple neurological, muscular, and cardiac diseases." (PMID 34361060, 2021).
kidney (2 papers, 2017 to 2020). "HIPK2 is also involved in acute kidney injury to CKD transition." (PMID 32701510, 2020).
HIPK2 also shares sentences with these, for which no sentence is quoted: gastric cancer (3 papers); Ureteral obstruction (3); cerebellar disorder (2); colitis (2); esophageal squamous cell carcinoma (2); follicular thyroid carcinomas (2); IgA nephropathy (2); pancreatic ductal adenocarcinoma (2); rheumatoid arthritis (2); adenocarcinoma (1); anemia (1); aneuploidy (1); carcinoma in situ (1); cerebellar ataxia (1); colon adenocarcinoma (1); colorectal tumor (1); Dystonia (1); ependymoma (1); glaucoma (1); hepatitis B virus infection (1); HIV-associated nephropathy (1); infection (1); inflammation (1); inflammatory bowel disease (1); intraepithelial cervical neoplasia (1); Kawasaki disease (1); lymphoma (1); membranous nephropathy (1); Obesity (1); pancreatitis (1).
A further 10 diseases each share a sentence with HIPK2 in 1 paper.